MYC (MYC proto-oncogene, bHLH transcription factor)
Diseases named in the same sentence as MYC in open-access papers (continued):
Sharing a sentence is not in itself a finding about the gene and the disease.
neuroblastoma (continued). "It has been well-documented that neuroblastoma cells that lack amplified MYCN generally express MYC rather than MYCN." (PMID 28713571, 2016). "MYC and MYCN activated miR-9, binding directly to the mir-9 locus in neuroblastoma cells." (PMID 26694467, 2015). "Results of this study have shown that S(+)-ibuprofen destabilized MYCN/MYC in neuroblastoma cell lines with or without MYCN amplification." (PMID 24173829, 2014). "One of the mechanisms by which MYC and MYCN are destabilized in S(+)-ibuprofen-treated neuroblastoma cells may be due to the augmented activation of calpains in response to UPR." (PMID 24173829, 2014). "A recent study also showed that non-MYCN amplified neuroblastomas of the unfavorable subset express high levels of MYC instead of MYCN, which appears to be the determining factor of their aggressiveness." (PMID 25017515, 2014). "In this previous work, a genome-wide search for MYCN targets was performed to identify clusters of genes that were directly regulated by MYC/MYCN or indirectly involved in MYCN-induced regulation, using a neuroblastoma cell line that allows conditional expression of MYCN." (PMID 23251412, 2012). "Finally, miR-9 activated by MYC/MYCN mediated E-cadherin down-regulation resulting in the activation of β-catenin, and VEGF, and metastases in human cancers, including neuroblastomas and breast tumors." (PMID 22752005, 2012). "Nevertheless, HMGA1 expression is influenced by MYCN status in neuroblastoma cells: this gene is significantly more expressed in MYCN-amplified neuroblastomas and it might be also activated by c-MYC or other transcription factors." (PMID 20459794, 2010). "Nevertheless, in localized-NA tumors, we did not observe that one MYC transcription factor dominates over the other, such as in the other neuroblastoma subtypes." (PMID 18851746, 2008). "A defined set of MYCN/c-MYC target genes was induced in stage 4-non-amplified but not in stage 4s-non-amplified neuroblastomas." (PMID 18851746, 2008). "Based on the relative expression of MYCN and c-MYC in neuroblastoma subtypes, we propose that elevated MYCN activity in stage 4s-NA tumors induces only a restricted set of MYCN/c-MYC target genes, whereas elevated c-MYC activity in stage 4-NA tumors induces a larger set of MYCN/c-MYC target genes." (PMID 18851746, 2008). "We used five neuroblastoma cell lines that either preferentially express high levels of MYCN (SH-EPMYCN, IMR5/75 (approximately 75 copies of MYCN), and Kelly (approximately 100-120 copies of MYCN)) or c-MYC (SJ-NB12 and SY5Y)." (PMID 18851746, 2008). "Neuroblastoma-derived cell lines that lack amplified MYCN generally express c-MYC rather than MYCN, often at higher levels than normal tissues." (PMID 18851746, 2008). "In neuroblastoma – an embryonal tumor with biological similarities to MB – the quassinoid NBT-272 has been demonstrated to inhibit cellular proliferation and to down-regulate c-MYC protein expression." (PMID 17254356, 2007). "Endogenous co-localization of ARMC12 and MYC protein was observed in ganglioneuroblastoma (GNB) or NB specimens, while their Pearson's coefficient was higher in NB tissues." (PMID 41510169, 2026). "Notably, in high-risk neuroblastoma cases lacking MYCN amplification, c-MYC overexpression can serve as a functional driver, conferring similarly poor clinical outcomes." (PMID 41002386, 2025). "Interestingly, we found that the non-MNA neuroblastoma cell-line CHLA-15 with MYC amplification was unusually sensitive to GLS inhibition with CB-839, in contrast to other lines." (PMID 39313128, 2024).
neuroblastoma (continued). "As these cell-lines are unusual amongst neuroblastoma lines in having MYC (c-MYC) amplification, and c-MYC-mediated global transcription is altered by glutamine deprivation, we posited that the relative sensitivity of CHLA-15/20 to GSK3203591 may be related to enhanced glutamine pathway dependence." (PMID 39313128, 2024). "However, how the dysregulated pre-mRNA splicing machinery and metabolism are orchestrated in MYC-driven neuroblastoma has not been well elucidated." (PMID 38488852, 2024). "Furthermore, pediatric neuroblastomas diverged from melanomas in that MYC mRNA showed strong positive rather than negative correlations with the same genes." (PMID 36768931, 2023). "Therefore, MYC but not MYCN or CD47 expression in neuroblastoma cells appears to be a significant regulator of T cell function in the tumor microenvironment." (PMID 36768931, 2023). "We tested the anticancer effects of disulfiram in four neuroblastoma cell lines with MYCN amplification (IMR-32, SK-N-DZ, SJ-N-TQ-24 and IGR-N91, hereafter named N91) and two without (SK-N-AS and SK-N-SH; note that these lines do express high levels of the oncogene MYC, according to depmap.org)." (PMID 37777587, 2023). "Reducing N-MYC levels in a neuroblastoma model with tunable MYCN expression mitigated cell death induction upon inhibition of mitochondrial translation and functionally validated the propensity of neuroblastoma cells for MYC-dependent cell death in response to the mitochondrial ISR." (PMID 37973789, 2023). "Our data reveals that WDR5 acts as a universal MYC recruiter at a small cohort of previously identified genes and highlights novel biological functions that may be coregulated by N-MYC and WDR5 to sustain the neuroblastoma state." (PMID 37336886, 2023). "We next utilized a panel of twelve neuroblastoma cell lines, including MYC- or MYCN-amplified and non-amplified clones, to test whether mitochondrial translation might be a common vulnerability in high-risk neuroblastoma." (PMID 37973789, 2023). "Immunoblots using the antibody recognizing both p-c-MYC(T58) and p-N-MYC(T58) showed that these phosphorylated forms are markedly upregulated in MYC-driven neuroblastoma and their levels correlated with sensitivity to DOXY-induced cell death in a panel of neuroblastoma and medulloblastoma models." (PMID 37973789, 2023). "In the solid tumors, there was a reduction in microvascularity and signs of increased hemorrhage, which might reflect collapse of tumor vasculature previously observed in the Omomyc tumor model after MYC inhibition and after MYCMI-6 treatment in a MYCN-amplified neuroblastoma xenograft mouse model." (PMID 36874405, 2022). "The adrenergic identity of the ADRN subtype of neuroblastoma cells is maintained by a transcriptional core regulatory circuit (CRC) of predominantly developmental regulators of neurogenesis including PHOX2B, GATA3 and ASCL1, whose expression is further maintained by high levels of MYC or MYCN." (PMID 36263020, 2022). "Currently, the clinical outcome of NB is mainly predicted based on age, tumor stage, mitotic nuclear rupture index, MYCN (Neuroblastoma MYC Oncogene) amplification and ALK (Anaplastic Lymphoma Kinase) expression." (PMID 36430219, 2022). "The hypothesis that MYC expression could induce non-cell autonomous effects is also supported by evidence of heterogeneous (focal) amplification of MYCN in neuroblastoma tumours." (PMID 34847775, 2021). "Our findings support a potential interplay between MYCN and c-MYC upon glutamine deprivation, and we initially sought to investigate the co-expression of CSC-related genes such as ALDH1A1 and ALDH1A3 with MYC member expression in the paediatric neuroblastoma patient data from the TARGET study." (PMID 32483461, 2020).
neuroblastoma (continued). "Interestingly, similar pathways that are used to avoid MYC transduction in iPS generation are potentially involved in the tumorigenesis of MYCN non-amplified neuroblastomas." (PMID 33585251, 2020). "In summary, our studies define the MK2/OCT4/c-MYC axis as a novel mechanism of MYC transcriptional activation in neuroblastoma that mediates resistance to 13-cisRA by rescuing 13-cisRA induced MYCN downregulation and is commonly found in progressive disease neuroblastomas." (PMID 32409685, 2020). "Furthermore, MYC has also been identified as an independent prognostic marker for poor survival in neuroblastoma and is predominantly expressed by non-MYCN-amplified tumors." (PMID 30744170, 2019). "Moreover, the inhibitors destabilized MYC and MYCN proteins in neuroblastoma cells." (PMID 29464082, 2018). "Moreover, the JQ1 and Milciclib combination both earlier and more effectively reduced the cell viability of the MYC-amplified Group 3 MB cell lines MB002, sD425, and D283 and the MYCN-amplified neuroblastoma cell line Kelly, as compared to the JQ1 and Palbociclib combination." (PMID 29511348, 2018). "The proteomic profiles of MYCN-amplified neuroblastoma cells treated with 10058-F4 or with specific MYCN short-hairpin RNA (shRNA) show similar affected Gene Ontology pathways and processes, where about half of the downregulated genes were previously characterized as MYC target genes." (PMID 28358317, 2017). "Taken together these data provide compelling evidence that JQ1 down regulates c-MYC driven transcription in medulloblastoma cell lines; these data are consistent with activity observed in hematologic malignancies and analogous to that seen in MYCN driven neuroblastoma." (PMID 24796395, 2014). "Hence, OSU-0312 was predicted to destabilize MYC and MYCN protein in neuroblastoma cells." (PMID 25017515, 2014). "Additionally, this study demonstrated that small molecule inhibitor of CSNK1e enzymatic activity, IC261, can reduce relative viability of c-MYC overexpressing HFF cells, in addition to MYC-overexpressing Tet21N cells and MYCN-amplifying IMR-32 neuroblastoma cells." (PMID 24275945, 2013). "Surprisingly, MYC regulation and cellular response to BET inhibition differ between hematologic and solid tumor models such as neuroblastoma, as MYC suppression was variable in MYC-expressing neuroblastoma cell lines and did not positively correlate with sensitivity to I-BET726." (PMID 24009722, 2013). "Early studies found that several c-MYC target genes were expressed in some neuroblastoma cell lines with MYCN amplification, but not all, suggesting that other cell specific factors may be important." (PMID 23226679, 2012). "Direct regulation of these target genes by MYCN/c-MYC was assessed by analyzing the binding of MYCN and c-MYC protein to target gene promoters using PCR- and array-based chromatin immunoprecipitation (ChIP and ChIP-chip, respectively) in different neuroblastoma cell lines." (PMID 18851746, 2008). "Because increased activity of MYCN in stage 4s-NA or c-MYC in stage 4-NA tumors should both result in high expression of shared target genes compared to localized-NA neuroblastomas, we analyzed known direct MYCN/c-MYC target genes, namely MDM2, DKC1, and PTMA, in neuroblastoma subtypes." (PMID 18851746, 2008). "However, our unbiased identification of the JMJD6 interactome only identified a subset of proteins involved in mRNA splicing and protein translation in neuroblastoma cells, suggesting that JMD6 may predominantly regulate protein homeostasis to facilitate MYC-mediated transformation." (PMID 38488852, 2024). "A functional MYCN/c-MYC signature also characterizes a fraction of aggressive NB without MYCN amplification, which suggests that increased MYC activity is a main driver of aggressiveness in neuroblastoma." (PMID 32309213, 2020). "Thus, MYCN, c-MYC, and HDAC8 may each contribute to neuroblastoma tumorigenesis." (PMID 30237861, 2018).
neuroblastoma (continued). "Frequent (6 of 8) intrachromosomal re-arrangements leading to induction of FOXR2 were also found in neuroblastoma; one tumor without such re-arrangement and FOXR2 induction exhibited focal MYC amplification." (PMID 40075567, 2025). "Across neuroblastoma cell lines, the subtype-specific difference in MYCN and MYC are not significant." (PMID 39825754, 2025). "In a panel of 32 neuroblastoma cell lines, MYCN or MYC amplification or translocation in adrenergic subtypes was accompanied by upregulated CBS expression, while MYC translocation/activation in mesenchymal cell lines was not." (PMID 35484422, 2022). "In our experiments, MYCN regulation by 13-cisRA was not attenuated by repeated exposure to the drug in neuroblastoma cells, but escape from sustained suppression of MYCN occurred via MYC transcriptional activation." (PMID 32409685, 2020). "Not unexpectedly, a subset of high-stage neuroblastoma tumors without MYCN amplification also have elevated ESC signature scores, in keeping with high MYC activity in these cells." (PMID 30504901, 2018). "MYCN-specific siRNA was not used, because mouse neuroblastoma cells express low basal levels of MYCN.Neuroblastoma cells were transfected for 72 h with negative control siRNA, siRNA-HADC8, siRNA-c-MYC, or siRNA-HDAC8 + siRNA-c-MYC." (PMID 30237861, 2018). "In contrast, more than 60% of non-MYCN amplified High-MKI neuroblastomas were MYCN protein (−)/(+/−) and MYC protein (−)/(+/−)." (PMID 29464082, 2018). "It is of interest to note that in this series of High-MKI neuroblastomas, there were a total of 22 tumors with prominent nucleolar formation which did not express excess amount of MYCN or MYC protein." (PMID 29464082, 2018). "Remarkably, the effector of all these circuits is the MYC protein, which seems to be the counterpart of MYCN in patients with MYCN-nonamplified neuroblastomas." (PMID 30134948, 2018). "In contrast, glutamine deprivation did not affect growth or survival of non-MYC amplified NCI-H345 SCLC cells and non-MYCN amplified SH-SY5Y neuroblastoma cells within the time frame tested." (PMID 28430666, 2017). "Compared to localized-non-amplified neuroblastomas, MYCN/c-MYC target gene expression gradually increases from stage 4s-non-amplified through stage 4-non-amplified to MYCN amplified tumors." (PMID 18851746, 2008). "Although c-MYC has been shown to regulate GLS expression via miR-23, we note that miR-23 levels are not significantly different in a comparison of MNA and non-MNA neuroblastomas." (PMID 39313128, 2024). "Combined analysis of copy number, gene expression, and NE scores in the CCLE cell line dataset revealed upregulation of MYC expression in the low-NE-score lines without copy-number gain, suggesting the transcriptional activation of MYC expression in the non-NE state for both SCLC and neuroblastoma." (PMID 37255415, 2023). "In agreement with MYC-independent mechanisms of BET inhibition that take place in some tumor contexts, ectopic overexpression of MYC/MYCN is not able to abrogate the suppressive activity of BETi in neuroblastoma and glioblastoma lines." (PMID 33668642, 2021). "We selected IMR-32, ACN and SH-SY5Y cell lines due to their different genomic characteristics: IMR-32 display MYCN (v-myc myelocytomatosis viral related oncogene, neuroblastoma derived) amplification, whereas ACN and SH-SY5Y do not, and SH-SY5Y exhibit strong c-MYC protein expression." (PMID 32737364, 2020). "We observed that c-MYC (but not MYCN) expression was consistently increased in neuroblastoma cell lines and patient-derived xenografts (PDX) established from clinical samples of PD neuroblastoma." (PMID 32409685, 2020). "We showed that MYC knockdown increased MYCN protein, but the cells did not regain their proliferative properties, suggesting that 13-cisRA-resistant cells are addicted to c-MYC, which functionally replaces MYCN in 13-cisRA-resistant neuroblastoma." (PMID 32409685, 2020).
neuroblastoma (continued). "Thus, as in retinoblastoma and neuroblastoma, high MDM2 was needed to maintain high-level MYCN but not MYC expression in SCLC cell lines." (PMID 33425720, 2020). "However, to our knowledge, recurrent focal amplifications of MYC, ZFHX3, KRAS, RRAS2, and CYTH1 have not been reported in neuroblastoma primary tumors before." (PMID 28924153, 2017). "Many transformed cell types, including neuroblastomas, express PVT1 and do not express MYC." (PMID 19419571, 2009). "However, transcriptional activity of MYCN or c-MYC as reflected by the transcript levels of direct MYCN/c-MYC target genes in relation to MYCN and c-MYC levels has not yet been defined in neuroblastoma subtypes." (PMID 18851746, 2008). "Alternative examples of autoregulation have been found for the following master TFs: FOSL1 in HNCC, MYC in colorectal cancer, ASCL1 in small lung adenocarcinoma, ISL1 in ovarian cancer, FOXC1 in triple-negative breast cancer, and MYCN in MYCN-amplified neuroblastoma." (PMID 38542080, 2024). "Since a subset of MYCN-non-amplified neuroblastomas have been shown to exhibit deregulated expression of (c)-MYC46, we investigated the expression of MYCN and MYC as well as total level of MYC-family proteins in the six cell lines using antibodies specific for MYCN, MYC or pan-MYC." (PMID 29968736, 2018). "Further, despite compelling evidence for MYC and RAS cooperation in vitro and in vivo to promote tumourigenesis, activation of RAS signal transduction does not constitute a preferred secondary pathway in neuroblastomas with MYCN deregulation in either human tumors or murine models." (PMID 16822308, 2006).